KLK14 (kallikrein related peptidase 14)
Description:
Serine-type endopeptidase with a dual trypsin-like and chymotrypsin-like substrate specificity. May activate/inactivate the proteinase-activated receptors F2R, F2RL1 and F2RL3 and other kallikreins including KLK1, KLK3, KLK5 and KLK11. May function in seminal clot liquefaction through direct cleavage of the semenogelin SEMG1 and SEMG2 and activation of KLK3. May function through desmoglein DSG1 cleavage in epidermal desquamation a process by which the most superficial corneocytes are shed from the skin surface. May be involved in several aspects of tumor progression including growth, invasion and angiogenesis.
Synonyms: KLK-L6
Tractability: Small molecule: a high-quality ligand is known. Antibody: UniProt places it where antibodies can reach, with high confidence; its Gene Ontology location is reachable by antibodies, with high confidence; UniProt predicts a signal peptide or a membrane-spanning region. PROTAC: a small molecule that binds it is known.
Target class: Serine protease; Enzyme; Serine protease PA clan; Serine protease S1A subfamily; Protease
Gene: Protein-coding gene on chromosome 19 (51,077,317 to 51,086,530, reverse strand). Ensembl gene ENSG00000129437.
Subcellular location: Secreted, extracellular space
Pathways (Reactome):
Developmental Biology: Formation of the cornified envelope
Gene Ontology:
Molecular function: serine-type endopeptidase activity
Biological process: epidermis morphogenesis; fertilization; negative regulation of G protein-coupled receptor signaling pathway; positive regulation of G protein-coupled receptor signaling pathway; proteolysis; seminal clot liquefaction; protein maturation
Cellular component: extracellular region; secretory granule
Genetic constraint (gnomAD): Loss-of-function variants: 21 observed, 22.34 expected, observed/expected ratio (o/e) 0.94, 90% interval 0.67 to 1.35. The upper end of that interval is the gene's LOEUF score, 1.35, which puts it in group 5 of 6, group 1 being the genes least tolerant of losing a copy. Missense variants: 320 observed, 326.32 expected, observed/expected ratio (o/e) 0.98, 90% interval 0.89 to 1.08. Synonymous variants: 133 observed, 136.05 expected, observed/expected ratio (o/e) 0.98, 90% interval 0.85 to 1.13.
Homologues: Orthologues: macaque KLK14 (95% identical), pig KLK14 (81% identical), dog KLK14 (79% identical), rat Klk14 (75% identical), guinea pig KLK14 (74% identical), mouse Klk14 (73% identical), rabbit KLK14 (51% identical), tropical clawed frog klk1 (40% identical), Drosophila melanogaster CG32808 (29% identical), Drosophila melanogaster Send2 (29% identical), Drosophila melanogaster CG3916 (27% identical), Drosophila melanogaster CG4477 (25% identical), and 7 more. Paralogues in human: KLK11 (47% identical), KLK5 (47% identical), KLK8 (47% identical), KLK12 (45% identical), KLK7 (43% identical), KLK2 (42% identical), KLK1 (42% identical), KLK4 (41% identical), KLK3 (41% identical), TMPRSS4 (31% identical), PRSS58 (28% identical), PRSS54 (20% identical).
Diseases named in the same sentence as KLK14 in open-access papers:
KLK14 is named in the same sentence as 42 diseases in open-access papers, as found by Europe PMC text mining. Sharing a sentence is not in itself a finding about the gene and the disease. The quoted sentences say what the papers report.
breast carcinoma (11 papers, 2002 to 2025). "Human kallikrein 14 (KLK14) is a steroid hormone-regulated member of the tissue kallikrein family of serine proteases, for which a prognostic and diagnostic value in breast cancer has been suggested." (PMID 16434994, 2006). "Klk14 expression has also been linked to prostate and breast cancers." (PMID 40753921, 2025). "KLK14 is a Protein Coding gene encoding a member of the kallikrein subfamily of serine proteases which has been reported to be associated with the progression of various cancers including prostate cancer and breast cancer." (PMID 36439479, 2022). "In conclusion, although our data provides further evidence to support the association of KLK14 with aggressive breast cancer, immunohistochemically determined KLK14 expression in primary breast cancer does not appear to have additional prognostic value for the surgical pathologist." (PMID 16434994, 2006). "In the present study, we carefully analysed KLK14 expression in normal and malignant breast tissue both on the RNA and protein level to further evaluate the potential value of KLK14 as a diagnostic marker in breast cancer." (PMID 16434994, 2006). "KLK12, KLK13, and KLK14 genes were downregulated in breast cancer, while KLK15 was overexpressed in more aggressive forms of prostate cancer." (PMID 33150763, 2020). "Further basic and clinical studies are warranted to clarify the potential role of KLK14 in the progression of breast cancer." (PMID 16434994, 2006). "The present study is the first to analyse KLK14 protein expression in a large cohort of human breast cancer specimens in comparison to matching normal breast tissues using a recently characterised KLK14-specific antibody." (PMID 16434994, 2006). "Other kallikrein genes, for example, KLK13 and KLK14, were also previously reported to be downregulated in breast cancer." (PMID 14710225, 2004). "Preliminary studies have shown that KLK14 is down-regulated at the mRNA level in prostatic, testicular, ovarian and breast cancer tissues and in two breast cancer cell lines." (PMID 12439719, 2002). "In this paper, we identify KLK14 as a new independent marker of unfavourable prognosis in breast cancer." (PMID 12439719, 2002). "We conclude that KLK14 expression, as assessed by quantitative reverse transcription–polymerase chain reaction, is an independent marker of unfavourable prognosis for breast cancer." (PMID 12439719, 2002). "In our studies of prognostic value of various kallikrein in cancer, we found down-regulation in breast cancer of KLK14 and in testicular cancer of KLK10." (PMID 11986781, 2002). "On the contrary, KLK14 mRNA expression was reported as a poor prognostic marker in breast cancers." (PMID 37176127, 2023). "On the other hand, KLK-mediated degradation of extracellular matrix proteins facilitates tumor cell invasion and metastasis, and higher serum levels of other kallikreins such as KLK5, KLK10, and KLK14 have been found in women with breast cancer when compared to healthy ones." (PMID 32344524, 2020). "The MSR1 cluster of KLK14 represents the strongest risk factor identified in non-familial breast cancer and an important risk factor for prostate cancer." (PMID 33381518, 2020). "Therefore, the main focus of the present study was to carefully and quantitatively analyse KLK14 protein expression in a large collection of human breast normal and tumour specimens to further evaluate the potential value of KLK14 for breast cancer prognosis." (PMID 16434994, 2006). "Using real-time RT-PCR we could clearly demonstrated KLK14 mRNA overexpression in breast cancer compared to normal breast tissue." (PMID 16434994, 2006). "To further characterise the value of KLK14 as a breast tumour marker, we have carefully analysed KLK14 expression in normal breast tissue and breast cancer both on the RNA level by real-time RT-PCR (n=39), and on the protein level (n=127) using a KLK14-specific antibody for immunohistochemistry." (PMID 16434994, 2006).
breast carcinoma (continued). "This equals the KLK14 elevation in breast cancer tissues we observed in 40 and 61% of cases on RNA and protein level, respectively, and thus may account for the KLK14 elevation in the serum of a proportion of breast cancer patients." (PMID 16434994, 2006). "KLK14 mRNA levels ranged from 0 to 1219 arbitrary units in breast cancer tissues, with a mean±s.e." (PMID 12439719, 2002). "Based on these collective findings, we hypothesised that KLK14 expression in malignant breast tissues may have prognostic/predictive value for patients with breast carcinomas." (PMID 12439719, 2002). "Thus, the presently available data leaves the question open whether KLK14 is a suitable biomarker for human breast cancer." (PMID 16434994, 2006). "Although the potential pathobiological role of KLK14 in breast cancer has not been elucidated, several lines of evidence suggest that KLK14, like many other kallikreins, may be causally involved in breast tumour progression." (PMID 16434994, 2006). "Hence, KLK14 expression may aid in predicting relapse, disease progression and/or survival in breast cancer patients." (PMID 12439719, 2002). "Thus, the identification of androgen regulated genes, such as KLK14, may help to define new targets for breast cancer treatment." (PMID 12439719, 2002). "KLK14 mRNA expression was analysed by LightCycler® RT-PCR in a set of archival formalin-fixed paraffin-embedded tissue specimens, consisting of 25 primary breast cancer (14 from node-positive tumours, 11 from node-negative tumours) and 14 normal breast tissue samples." (PMID 16434994, 2006). "With respect to breast cancer in particular, several kallikrein family members, namely KLK3, KLK5, KLK6, KLK10, KLK12, KLK13, and KLK14 were shown to be differentially expressed at the mRNA or protein levels within the cancerous tissues or serum of such patients." (PMID 16434994, 2006). "Interestingly, the results obtained for KLK14 in this study are comparable to those obtained for KLK3, KLK6 and KLK15 in breast cancer and KLK4, KLK5 and KLK10 in ovarian cancer, in that high expression of these kallikrein genes also correlated with patient prognosis." (PMID 12439719, 2002).
ovarian carcinoma (10 papers, 2002 to 2022). A malignant neoplasm originating from the surface ovarian epithelium. "Another study showed that seven genes (KLK5-8, KLK10, KLK11, and KLK14) were elevated in ovarian cancer tissue samples and cell lines compared with the healthy ovary." (PMID 33150763, 2020). "Four KLKs (KLK4–6 and KLK15) are linked to the poor prognosis of ovarian cancer patients, while higher KLK9 and KLK14 levels are associated with a favorable course of the disease." (PMID 25436002, 2015). "It has been reported that at the transcriptional level, KLK4–8, KLK10 and KLK14 are highly expressed in ovarian cancer tissues." (PMID 24043563, 2014). "High protein levels of KLK4–7 and KLK10 have been found in ovarian cancer tissues, while KLK5–8, KLK10, KLK11, KLK13 and KLK14 were found in ascites fluid from ovarian cancer patients as reviewed." (PMID 24043563, 2014). "Expression of the kallikrein cluster including KLK4 to KLK14 has previously been reported in ovarian cancer." (PMID 22102857, 2011). "Hormonal regulation studies in breast and ovarian cancer cell lines indicate that KLK14 expression is controlled by the androgen receptor in response to steroid hormones, particularly androgens and progestins (our unpublished data)." (PMID 12439719, 2002). "Similar to other kallikrein genes, KLK14 was found to be regulated by steroid hormones, particularly androgens and progestins, in breast and ovarian cancer cell lines." (PMID 12439719, 2002). "All KLKs, except KLK14, were predicted to be targets for ovarian cancer-dysregulated miRNAs." (PMID 20354523, 2010). "Whereas in the normal ovary only KLK10 and to a lesser extent KLK11 and KLK14 are expressed, most of the members of the KLK family are considerably upregulated in ovarian cancer." (PMID 30811511, 2019). "The hierarchical clustering revealed a group of proteins that have previously been reported to be expressed at elevated levels in ovarian cancer serum samples, including: CA125 (MUC16), HE4, MSLN, MK, KLK8, KLK11, NECT4, FOLR1, as well as KLK13, KLK14, and IL6." (PMID 35804849, 2022). "Significantly better response to platinum-based chemotherapy was seen in patients with KLK14-positive ovarian cancer [67 of 70 (95.7%)], compared to those with KLK14-negative tumor [58 of 72 (77.3%)]." (PMID 30791431, 2019).
prostate carcinoma (10 papers, 2014 to 2025). A carcinoma that arises from epithelial cells of the prostate gland. "AGRN was also proposed as a substrate of Kallikrein-related peptidase 14 (KLK14), a serine protease involved in prostate cancer (PCa) pathogenesis." (PMID 40136513, 2025). "Herein, we first demonstrated how miR-378 exerts anti-prostate cancer (PCa) actions by influencing multiple target genes, including KLK2, KLK4, KLK6, and KLK14, which are implicated in PCa development, cell proliferation, and cell survival." (PMID 35681793, 2022). "Kallikrein‐related peptidase 14 (KLK14) is one of the several secreted KLK serine proteases involved in prostate cancer (PCa) pathogenesis." (PMID 31630475, 2020). "Most notably, KLK14 levels were found to predict poor outcomes in prostate cancer patients, and elevated levels of both transcript and protein were found in malignant breast cancer tissues." (PMID 32575583, 2020). "In this study, KLK1, KLK4, KLK9, and KLK14 were strongly decreased in prostate cancer samples compared with controls." (PMID 33150763, 2020). "Our results point to the fact that KLK1, KLK2, and KLK14 (only in recurrent prostate cancer tissues) are underexpressed in prostate cancer tissues, while KLK3, KLK4, KLK8, and KLK9 are overexpressed in both recurrent and non-recurrent tissues." (PMID 33150763, 2020). "KLK-14 is another protease that is involved in prostate cancer progression, and its expression is elevated in metastatic and castration-resistant prostate cancer cells." (PMID 32948029, 2020). "We identified that KLK14 is overexpressed in advanced prostate cancer and acts on various substrates involved in adhesion, migration, and invasion of cancer cells, thus modulating genes and signaling pathways essential for prostate cancer progression." (PMID 31630475, 2020). "In conclusion, we propose that KLK1, KLK2, KLK3 KLK4, KLK8, KLK9, and KLK14, which are differentially expressed in prostate cancer, could be used as promising biomarkers of prostate cancer progression." (PMID 33150763, 2020). "Expression of kallikrein-related peptidase 14 (KLK14), which is likely to have a major role in seminal clot liquefaction, indicates an adverse clinical outcome of prostate cancer patients as elevated KLK14 mRNA and protein levels have been associated with more aggressive tumors." (PMID 24809052, 2014). "A recent report has identified a pericellular network of KLK4, KLK14, MMP3, and MMP9 that are involved in initiation and promotion of prostate cancer cell metastasis; however, the function of KLK14 in this complex was not identified." (PMID 32575583, 2020).
colon carcinoma (5 papers, 2013 to 2022). "Further, KLK14 has been linked to oncogenic signaling in colon cancer where it activates PAR2 to induce ERK1/2 signaling and cellular proliferation." (PMID 24158494, 2014). "Since HT29 cells present high expression of both trypsinogen and KLK14, we selected this colon carcinoma-derived cell line for further study." (PMID 23991105, 2013). "In the present study, we demonstrate that the autocrine action of trypsin and KLK14 promoted colon cancer cell proliferation through the activation of PAR2." (PMID 23991105, 2013). "KLK14 mRNA was present in all human colon cancer cells analyzed, while trypsinogen expression was observed only in Caco-2 and HT29 cell lines." (PMID 23991105, 2013). "KLK14 acts at the cleavage site of PAR-2 to induce ERK1/2 activation, thus promoting colon cancer proliferation." (PMID 34395235, 2021). "Most recently, KLK14 was found to be expressed and be able to activate PAR2 in colon cancer cells." (PMID 23991105, 2013). "Many in vitro studies have shown that KLK6 may undergo autoactivation or become activated by other proteases including other KLKs, such as KLK14 and KLK5, for which overexpression in human colon tumors has been demonstrated in our previous report and in ongoing work (unpublished data)." (PMID 35883559, 2022).
inflammatory skin disease (4 papers, 2021 to 2025). Inflammatory skin disorders covers a broad category that includes many conditions ranging in severity, from mild itching to grave medical health complications These disorders are common in people of all ages and races. "It counteracts inflammation and oxidative stress in inflammatory skin diseases, obesity, and associated metabolic disorders, in part by inhibiting the kallikrein proteases KLK7 and KLK14." (PMID 40975878, 2025). "Many of the proteases present in tumors activate PAR signaling, including elevated levels of KLK14 in tumors and inflammatory skin diseases such as the Netherton syndrome." (PMID 39971938, 2025). "In particular, the skin-derived KLK5, KLK7, and KLK14 have recently gained increasing attention as promising therapeutic targets in inflammatory skin disorders and cutaneous malignancies, such as the widespread atopic dermatitis and the rarer Netherton syndrome." (PMID 41516101, 2025).
Netherton syndrome (4 papers, 2017 to 2025). Netherton syndrome (NS) is a skin disorder characterized by congenital ichthyosiform erythroderma (CIE), a distinctive hair shaft defect (trichorrhexis invaginata; TI) and atopic manifestations. "SPINK5 specifically inhibits KLK5, KLK7, and KLK14 activity, and mutations in SPINK5 cause Netherton Syndrome, a severe skin disorder." (PMID 28414719, 2017). "LEKTI can diminish the activities of epidermal serine proteases such as KLK5, KLK6, KLK7, KLK13, and KLK14 in skin, and a mutation in the SPINK5 gene is characteristic of Netherton syndrome, which presents with serious dehydration, itching, and chronic skin inflammation." (PMID 35955819, 2022).
atopic dermatitis (2 papers, 2025). "Interestingly, KLK5 and KLK14 were previously shown to activate PAR2 expressed in keratinocytes and intense KLK14 staining was observed in atopic dermatitis and rosacea patients' squamous and granular skin layers." (PMID 40621923, 2025). "For example, a stimulated induction of KLK14 expression reached nearly 3000‐fold upon primary normal human epidermal keratinocyte treatment with S. aureus‐conditioned medium, a finding potentially relevant for atopic dermatitis." (PMID 40621923, 2025).
breast tumour (2 papers, 2002 to 2006). "Although one study reported loss of KLK14 expression in 21 of 25 analysed breast tumours in comparison to normal breast tissue, another study demonstrated abundant KLK14 expression in tumours and an association of high KLK14 expression with advanced disease." (PMID 16434994, 2006). "In summary, we quantified KLK14 expression in breast tumours and found that high KLK14 expression is associated with decreased DFS and OS in both univariate and multivariate analysis." (PMID 12439719, 2002). "In 40% (10 out of 25) of the breast tumours analysed, we detected an at least two-fold upregulation in KLK14 mRNA expression compared to the mean KLK14 expression in normal breast tissue." (PMID 16434994, 2006). "KLK14 RNA expression as quantified by real-time RT-PCR was significantly more abundant in breast tumours compared to normal breast tissue (P=0.027), an issue that had not been clarified recently." (PMID 16434994, 2006). "The cutoff value in this study for KLK14 positive and negative tumours was defined by its ability to predict disease-free and overall survival and resulted in the definition of KLK14 positivity in 31% of breast tumours." (PMID 16434994, 2006). "Altogether, mean KLK14 mRNA expression in breast tumours was 2.3-fold more abundant compared to the mean expression of KLK14 mRNA in normal breast tissues; this difference was statistically significant (P=0.027, two-tailed Mann–Whitney U-test)." (PMID 16434994, 2006). "However, our data are in agreement with another quantitative RT-PCR study that described much more abundant KLK14 expression (in 55 of 178 breast tumours) and a clear correlation of KLK14 expression and poor prognosis." (PMID 16434994, 2006). "Patients with KLK14-positive breast tumours were more likely to have advanced stage (III) disease." (PMID 12439719, 2002).